TNF (tumor necrosis factor)
Diseases named in the same sentence as TNF in open-access papers (continued):
Sharing a sentence is not in itself a finding about the gene and the disease.
Sepsis (continued). "TNF-α induces organ damage by activating neutrophils and endothelial cells as well as coagulation abnormalities in patients with sepsis." (PMID 18601748, 2008). "In our murine model of LPS-induced sepsis, TNF-α blood concentrations rise rapidly and are profoundly decreased by the co-administration of an A2A AR agonist, ATL313." (PMID 18937852, 2008). "Inoculation of experimental animals with TNF-α alone reproduces many of the fundamental pathophysiologic alterations typical of sepsis." (PMID 18937852, 2008). "Elevated TNF-α levels are regarded to be adverse for the antimicrobial functions of PMNs and consequently for the outcome from major infections such as sepsis." (PMID 18447905, 2008). "We have found that elevated IL-10 and decreased TNF in the first few hours of experimental sepsis is correlated with increased survival." (PMID 18937852, 2008). "Elevated serum IL-1β, IL-6, IL-8, and TNF-α levels have beenfound in both the neonatal and adult sepsis." (PMID 18274637, 2007). "It confirms the notion that plasma levels of IL-6, KC, MIP-2, and TNF soluble receptor I (sTNFR-I) were reliable predictors of lethal outcome in experimental, or clinical sepsis." (PMID 17987129, 2007). "Recently, preventive treatment with bupropion-amfebutamone, a noradrenalinedopamine reuptake inhibitor, was shown to reduce TNF-α release and mortality in a murine model of severe sepsis." (PMID 17477857, 2007). "Infusion of site-inactivated factor VIIa reduced production of cytokines, including IL-6, IL-8 and soluble TNF (tumor necrosis factor) receptor 1 in a baboon model of sepsis." (PMID 17450221, 2007). "The pathogenesis of lethal sepsis remains obscure, but is mediated in part by excessive release of early (e.g., TNF and IL-1) and late (e.g., HMGB1) proinflammatory cytokines." (PMID 17987129, 2007). "Lipotechoic acid, a product of Staphylococcal organisms, promotes production of tumor necrosis factor-alpha (TNF-α) and leads to the development of sepsis and septic shock." (PMID 17448226, 2007). "Sepsis leads to early release of the cytokines; tumor necrosis factor (TNF)-α and interleukin (IL)-1β which are primarily produced by macrophages." (PMID 17397554, 2007). "Sepsis and endotoxin activate monocytes, macrophages,lymphocytes, fibroblasts, and endothelial cells that produce and secrete IL-1, TNF-α,α-interferon, IL-6, IL-8, and other proinflammatory cytokines." (PMID 18274637, 2007). "The pathogenesis of sepsis is mediated in part by bacterial endotoxin, which stimulates macrophages/monocytes to sequentially release early (e.g., TNF, IL-1, and IFN-γ) and late (e.g., HMGB1) pro-inflammatory cytokines." (PMID 17987129, 2007). "In contrast, although TNF-α concentrations failed to predict the evolution of organ dysfunction, or early or late mortality, TNF-α concentrations were significantly higher in patients with septic shock than in those with severe sepsis." (PMID 17448250, 2007). "In sepsis, both increased NO generation and the presence of LPS can trigger the release of platelet-derived exosomes, whereas thrombin or TNF-α induces the generation of phosphatidylserine-rich particles." (PMID 17894858, 2007). "Theaim of this study is to determine serum IL-1β, IL-6, IL-8, and TNF-α levels inneonatal sepsis at the time of diagnosis and after therapy and to show themeaningful on the follow up." (PMID 18274637, 2007). "The generation of pro-inflammatory cytokines during sepsis, including IL-1, IL-6, and IL-8 as well as TNF-alpha activates the endothelial lining cells." (PMID 17062126, 2006). "This allowed us, in collaboration with these New York tumour researchers, to propose novel roles for TNF in immunity and disease pathogenesis in malaria and sepsis." (PMID 17029647, 2006).
Sepsis (continued). "Evidence of causality has been observed in an animal model in which prior administration of a neutralizing antibody to TNF prevented the sepsis encephalopathy, generated through experimental pancreatitis, a standard functional example of sepsis." (PMID 17029647, 2006). "Triggers for their release include TNF, and they are increased in the circulation in systemic inflammatory states such as sepsis and trauma, as well as inducing inflammatory cytokine release themselves." (PMID 17029647, 2006). "Patients with septicemia generate high levels of pro-inflammatory cytokines like tumor necrosis factor [TNF]." (PMID 16571116, 2006). "This is the first time, to our knowledge, that an agent with anti-TNFα properties is applied in an experimental model of sepsis triggered by a multidrug-resistant pathogen." (PMID 15978135, 2005). "Its specific anti-TNFα effect has also been considered as the mode of action in experimental sepsis by E.coli." (PMID 15978135, 2005). "The present study revealed that intake of thalidomide considerably prolonged survival in experimental sepsis by multidrug-resistant P.aeruginosa an effect probably attributed to decrease of serum TNFα." (PMID 15978135, 2005). "Thalidomide is an inhibitor of tumour necrosis factor-alpha (TNFα) that has been proven effective for the treatment of experimental sepsis by Escherichia coli." (PMID 15978135, 2005). "Thalidomide has been proved effective in reducing serum TNFα in experimental sepsis induced by endotoxins and E.coli by a mechanism differing from monoclonal antibodies." (PMID 15978135, 2005). "Intake of thalidomide considerably prolonged survival in experimental sepsis by MDR P.aeruginosa an effect probably attributed to decrease of serum TNFα." (PMID 15978135, 2005). "Additionally, DYY inhibited inflammation (TNF-α, IL-1β, and IL-6), cell apoptosis, and promoted proliferation in sepsis, as well as the promotion of tight junction proteins (claudin-1, occludin, and ZO-1)." (PMID 41948377, 2026). "TNF-α and IL-1 are particularly significant among the proinflammatory cytokines; they are biologically interconnected, act synergistically, and play a major role in the clinical manifestations of sepsis." (PMID 41563955, 2026). "Mechanistically, transcriptomic analyses revealed that OLA@SPA MPs reversed sepsis-associated gene expression signatures, particularly by downregulating key pro-inflammatory pathways such as NOD-like receptor and tumor necrosis factor (TNF) signaling." (PMID 41809387, 2026). "Importantly, therapeutic strategies targeting single inflammatory mediators, such as anti-TNF-α antibodies, have failed in clinical sepsis, highlighting the potential advantage of agents like MLT that simultaneously modulate multiple signaling pathways." (PMID 41614949, 2026). "This study highlights the potential of ET evaluation, particularly of TNFα production, as a rapid and specific point-of-care test to identify high-risk patients and distinguish sepsis from non-complicated infections." (PMID 40862819, 2025). "In addition, cytokines such as IL-6 and TNF-α as well as markers of endothelial dysfunction have important prognostic value in the immunopathological process of sepsis." (PMID 41315982, 2025). "The identification of TNF as an early mediator of sepsis, largely through animal models, paved the way for the development of anti-TNF biologics like infliximab, etanercept, and adalimumab as cornerstone therapies for RA, Crohn’s diseases, and ulcerative colitis." (PMID 40303397, 2025). "Similarly, mRNA levels of proinflammatory mediators, including TNF-α, IL-1β, and IL-6, were upregulated in the lung tissue following sepsis." (PMID 40421173, 2025). "A decreased sTREM-1/tumor necrosis factor (TNF) ratio may promote theprogression from sepsis to severe sepsis, and potentially to septic shock." (PMID 40776964, 2025).
Sepsis (continued). "A recent study further showed that luteolin (20 mg/kg) inhibits the AKT1/nitric oxide synthase 2/cathepsin G (AKT1/NOS2/CTSG) axis, thereby blocking caspase-11 and GSDMD activation, leading to reduced IL-1β and TNF-α release, thus mitigating sepsis-induced pulmonary injury." (PMID 41394141, 2025). "TNF-α is believed to be an essential mediator in sepsis, primarily generated by Kupffer cells." (PMID 40977719, 2025). "The pro-inflammatory cytokines, TNF-α and IL-6, play a crucial role in the initial phase of sepsis." (PMID 40885907, 2025). "For instance, cytokines such as TNF-α and IL-6, produced during sepsis, play a key role in organizing inflammatory responses and may indirectly support tumor formation." (PMID 40028316, 2025). "In a sepsis model of Sprague Dawley rats induced via a caecal ligation and puncture procedure, it was demonstrated that the inflammatory response, including TNF-α, involves sepsis-induced changes in behavioral stereotypy, which suggests that TNF-α plays a vital role in the early prediction of SAE." (PMID 40529149, 2025). "Indeed, the infusion of epinephrine after LPS administration in humans reduces the levels of TNF-α and increases IL−10 levels in whole blood adding support that catecholamines serve an anti-inflammatory role in sepsis." (PMID 39968295, 2025). "Indeed, the higher serum creatinine, alanine transaminase, and cytokines (TNF-α and IL-6) with the lower SCFAs (propionate, acetate, and butyrate) in patients with sepsis compared with the healthy control was demonstrated." (PMID 41444762, 2025). "TNF-α-producing Gr-1+ monocytes significantly contribute to lung injury in sepsis, while TNF-α produced by alveolar macrophages play a critical role for the recruitment and activation of monocytes and neutrophils, essential for the advancement of LPS-induced ALI." (PMID 40872499, 2025). "Moreover, sepsis induction leads to the generation of proinflammatory cytokines such as IL-1β, IL-18, and TNF-α." (PMID 40770673, 2025). "TNF‐α is an early indicator of endotoxin exposure in animals with sepsis." (PMID 39792082, 2025). "In sepsis, the level of TNF-α in the blood can reach 1 ng/mL." (PMID 40265442, 2025). "Signal transduction studies showed that the activation of TLR4, an essential component of the innate immune system, by sepsis causes downstream enhancement of PI3K/MAPK signaling, nuclear translocation of NFκB, and subsequent generation of proinflammatory cytokines such as TNFα and interleukins." (PMID 40143165, 2025). "However, more recent meta-analyses have demonstrated a significant reduction in 28-day mortality with TNF-α blockade in sepsis, reflecting the evolving understanding of cytokine modulation in critical illness and ongoing debate in sepsis research." (PMID 40481519, 2025). "Moreover, it must be noted that most data on TNF-α/IL-1β/mediated myocardial injury come from sepsis, ischemia-reperfusion, or animal models." (PMID 40710793, 2025). "TNF-α is the first pro-inflammatory cytokine released into circulation during sepsis." (PMID 41517447, 2025). "Similarly, human studies on sepsis patients have shown a time-dependent reduction in plasma levels of IL-1β, IL-6, IL-8, and TNF in those receiving treatment with the β2 microglobulin adsorption column." (PMID 40234407, 2025). "In addition, studies have shown that SFI can alleviate the “inflammatory storm” in sepsis by inhibiting excessive inflammatory responses (such as reducing TNF-α and IL - 6 levels)." (PMID 41031112, 2025). "We inhibited autophagy by administering 3-MA and detected the mRNA level of the inflammatory factor TNFα to further clarify whether LXR protects against sepsis-induced ALI by enhancing autophagy." (PMID 40994643, 2025). "Similarly, GYY-4137 significantly reduced the serum levels of TNFα and interleukin-6 (IL-6), as well as iNOS expression, in mice with sepsis." (PMID 40559470, 2025).
Sepsis (continued). "While TNF-α and IL-6 are established mediators of the septic cascade the stronger modulation of IL-40 in our study supports its potential role as a novel biomarker of disease activity and treatment response in sepsis." (PMID 41196905, 2025). "Similarly, in the present study, TNF-α levels were significantly elevated (p < 0.05) in all sepsis groups (G3–G7) compared to the control (G1) and sham (G2) groups." (PMID 41517447, 2025). "Likewise, studies have shown that macrophage apoptosis is significantly increased in sepsis, accompanied by the activation of signaling pathways involving Fas/FasL and TNF-related pathways." (PMID 40364841, 2025). "Local inflammation and sepsis are primarily mediated by IL-6 and TNF-α." (PMID 39999222, 2025). "Similarly, sepsis involves massive pro-inflammatory cytokine release (e.g., TNF-α, IL-1β, IL-6), triggering systemic inflammatory responses and tissue injury." (PMID 40657502, 2025). "As a result, our TNF measurements may differ from those obtained by other sepsis research laboratories." (PMID 40433392, 2025). "In a mouse model of severe acute respiratory syndrome coronavirus 2 (SARS-CoV-2) infection, hemophagocytic lymphohistiocytosis, and sepsis, blocking tumor necrosis factor-alpha (TNF-α) and interferon-gamma (IFN-γ) prevents cell death and reduces the development of cytokine storm." (PMID 41142251, 2025). "Notably, studies have shown that increased plasma IL-6 and TNF-α levels in sepsis patients are correlated with mortality." (PMID 40496000, 2025). "In sepsis-induced acute lung injury, the incidence of macrophage pyroptosis were increased, followed by overexpression of pro-inflammatory mediators such as iNOS, IL-1β and TNF-α, and observable pulmonary tissue lesions." (PMID 40028334, 2025). "TNF-alpha and IL-6 are two major inflammatory cytokines that are elevated in patients with bacteremia and sepsis, and their production by the innate immune system in response to bacterial infection is likely a major driver of the general inflammatory responses observed." (PMID 39835799, 2025). "This can explain why TNF blockade increases the mortality rate of patients with sepsis." (PMID 40699834, 2025). "The pathogenesis of sepsis involves the initial excessive activation of the immune system, resulting in the release of pro-inflammatory cytokines such as Interleukin-1 beta (IL-1β), Interleukin-6 (IL-6) and Tumor Necrosis Factor-alpha (TNF-α)." (PMID 40688672, 2025). "The importance of this mechanism is underscored by the finding that treating mice with recombinant GAPDH protein has an anti-inflammatory effect, reducing TNFα levels in a sepsis model (exogenous GAPDH likely sequesters TNFα mRNA without undergoing malonylation)." (PMID 41107644, 2025). "The presence of interleukin (IL)‐2, IL‐4, IL‐5, IL‐6, IL‐8, IL‐10, TNF‐α and interferon‐γ was significantly more evident in all three cell culture media transfected with plasma from sepsis patients than in controls, indicating that the transfected cells potentially underwent necroptosis." (PMID 40318009, 2025). "In comparison, despite associations linking high levels of TNFα with increased mortality, its exact role remains elusive as no direct connection between TNFα and sepsis severity has been made." (PMID 40534875, 2025). "Similarly, a 53-year-old man from Turkey with HS, amyloidosis, sepsis, and acute renal failure was treated with TNF inhibitors like adalimumab, which helped manage his HS complications despite persistent renal impairment​28." (PMID 39898256, 2025). "Tumor necrosis factor-α (TNF-α) is a major mediator of sepsis." (PMID 41357527, 2025). "However, as for TNFα, the magnitude of the rise in circulating interleukin due to LPS sepsis shows circadian dependency." (PMID 39968295, 2025). "Patients with sepsis had reduced TNF production as compared to healthy controls." (PMID 40433392, 2025).
Sepsis (continued). "In sepsis models involving both standard and multidrug-resistant bacteria, these peptides alleviated tissue pathology by repressing pro-inflammatory mediators (TNF-α, IL-1β) and augmenting anti-inflammatory responses driven by IL-10, TGF-β, and lipoxins." (PMID 41440897, 2025). "Janus kinase signal transducer and activator of transcription (JAK/STAT) pathway is a critical cellular signal transduction pathway and an important pathway for cytokine signal transduction in the pathogenesis of sepsis, such as tumor necrosis factor-α (TNF-α) and interleukin-6 (IL-6), among others." (PMID 40338919, 2025). "Furthermore, coincubation of OLA@MΦ NPs released from the capsules with IL‐1β, IL‐6, TNF‐α, and LPS, key mediators of the cytokine storm during sepsis, showed dose‐dependent binding of the NPs to these cytokines." (PMID 39836501, 2025). "Our results indicated that acute abdomen III could lower blood concentrations of IL-6, IL-1β, and TNF-α in the sepsis model, consistent with previous findings." (PMID 40582762, 2025). "Second, through anti‐inflammatory and immunomodulatory effects: β‐blockers suppress the nuclear factor‐κB pathway, leading to decreased release of pro‐inflammatory cytokines (e.g., TNF‐α, IL‐6) and alleviating sepsis‐induced cytokine storm‐mediated myocardial injury." (PMID 41324108, 2025). "We detected the expression level of Acod1 mRNA in peripheral blood neutrophils of healthy volunteers and sepsis patients, and determined the concentration of pro‐inflammatory factor TNF‐α in peripheral blood, as well as the content of NETs' characteristic components CitH3‐DNA and MPO‐DNA." (PMID 40586264, 2025). "Si-CSN6 reduced IL-1β, IL-6, and TNF-α levels in an in vitro sepsis model (n = n= 6 per group)." (PMID 40595050, 2025). "LPS-induced sepsis triggers a systemic cytokine storm marked by sharp increases in pro-inflammatory mediators, particularly interleukin-6 (IL-6) and tumor necrosis factor-alpha (TNF-α), both of which play central roles in sepsis pathogenesis and organ dysfunction." (PMID 40871061, 2025). "The most well-known approach is the use of anti-TNF agents in clinical trials of sepsis." (PMID 40699834, 2025). "TNF-α, a classic pro-inflammatory factor, is rapidly released during the early stages of the inflammatory response and is significantly correlated with mortality in sepsis." (PMID 40176879, 2025). "Furthermore, ALA protected BBB permeability, decreased neuroinflammation by reducing TNF-α and IL-1β levels and acutely increased antioxidant activity in brain structures after sepsis induction." (PMID 40077661, 2025). "This contrasts with TNFα, which is a pro-inflammatory cytokine often elevated in sepsis, and its reduction alongside NE may indicate a balancing effect between pro-inflammatory and immune-regulatory pathways during Esmolol treatment." (PMID 40421209, 2025). "In sepsis, alpha7nAChR signaling controls the production of tumor necrosis factor (TNF) in macrophage which is believed to be a major factor triggering septic shock U-STAT3 but not P-STAT3 contributes to the reduction of TNF production and modulates alpha7nAChR signaling." (PMID 40725945, 2025). "Additionally, differences in interleukin and tumor necrosis factor levels and immunological changes in resuscitation are similar to those in sepsis." (PMID 40363899, 2025). "Studies have shown that ursolic acid may prevent sepsis–induced acute kidney injury in mice by inhibiting reactive oxygen species and inflammatory cytokines in the kidneys, including TNF–α, IL–1β, and IL–6." (PMID 40005889, 2025). "In addition, the TNF-α/NF-κB pathway, a major inflammatory driver in sepsis, is modulated by IL-1R2 activity." (PMID 40699828, 2025). "Notably, inflammatory cytokines including TNF-α, IL-1β, and IL-6 serve as critical regulators in sepsis pathogenesis." (PMID 40775729, 2025).